XRCC4 (X-ray repair cross complementing 4)
Diseases named in the same sentence as XRCC4 in open-access papers (continued):
Sharing a sentence is not in itself a finding about the gene and the disease.
glioblastoma (14 papers, 2017 to 2023). The most malignant astrocytic tumor (WHO grade IV). "An important component of this pathway is the XRCC4 protein, which has recently been discovered to be a direct target of miR-151a in resistant glioblastoma cells." (PMID 35804989, 2022). "Restoring miR-151a expression sensitized temozolomide-resistant glioblastoma cells through inhibition of XRCC4-mediated DNA repair." (PMID 35804989, 2022). "Exosomal miR-151a sensitized temozolomide (TMZ)-resistant glioblastoma cells to TMZ by interacting with X-ray repair cross-complementing 4 (XRCC4)." (PMID 36142830, 2022). "The reduction of XRCC4 is suppressive to tumor progression, because XRCC4 enhances double strand repair in glioblastoma." (PMID 35582574, 2019). "In glioblastoma, loss of BRCA2, LIG4, or XRCC4 was associated with more frequent occurrence of complex genome rearrangements." (PMID 30420702, 2018). "Temozolomide (TMZ)-resistant glioblastoma (GBM) cells become sensitive to TMZ through the targeting of the X-ray repair cross-completing 4 (XRCC4) by exosomal miR-151a." (PMID 31533332, 2019). "A prior study revealed that SBF2-AS1, an upregulated lncRNA in glioblastoma multiforme cells, promotes temozolomide (TMZ) resistance by functioning as a ceRNA for miR-151a-3p, disinhibiting its target XRCC4 and enhancing DNA repair." (PMID 38012734, 2023). "We further analyze the cancers without normal tissues in the TIMER database via the GEPIA database, and the results showed that XRCC4 was significantly upregulated in lymphoid neoplasm diffuse large B-cell lymphoma (DLBC), glioblastoma (GBM), LGG and THYM." (PMID 36765282, 2023).
Immunodeficiency (12 papers, 2013 to 2026). Failure of the immune system to protect the body adequately from infection, due to the absence or insufficiency of some component process or substance. "Genetic ablation of other members of the NHEJ pathway (Ku70, Ku80, DNA-PKCS, XRCC4, or Lg IV) generates a severe DNA repair deficiency, promoting global premature replicative senescence and B and T immunodeficiency." (PMID 23301049, 2013). "XRCC4-deficient individuals show a junctional immunoglobulin diversification defect but have normal immunoglobulin concentrations and lack clinical signs of immunodeficiency." (PMID 30013564, 2018). "XLF, a key protein in NHEJ, was discovered independently through yeast two-hybrid screening for XRCC4 interactors and investigations of a group of patients with growth retardation, microcephaly and immunodeficiency characterized by a profound T + B lymphocytopenia." (PMID 24636752, 2014). "These in vivo results reveal new functional interplays between XRCC4 and PAXX, ATM and Xlf in mouse development and provide new insights into the understanding of the clinical manifestations of human XRCC4-deficient condition, in particular its absence of immune deficiency." (PMID 34519267, 2021). "It has been previously noted that XRCC4-patients have usually no clinical immunodeficiency, unlike in the other syndromes affecting the NHEJ system." (PMID 40114033, 2025). "XRCC4 is also the causative gene of human microcephalic primordial dwarfism (MPD), and various XRCC4 mutations have been observed in MPD patients without any overt immunodeficiency." (PMID 35000298, 2022). "Interestingly, given that XRCC4 is required to stabilise LIG4, it is surprising that to date, none of the patients described exhibit clinical immunodeficiency, despite the marked DNA-DSB repair defect." (PMID 27717373, 2016).
glioma (11 papers, 2009 to 2023). A benign or malignant brain and spinal cord tumor that arises from glial cells (astrocytes, oligodendrocytes, ependymal cells). "It has also been shown that glioma sensitivity to TMZ is related to polymorphisms in the XRCC4 gene." (PMID 32746854, 2020). "We further evaluated the interaction between the LIG4 rs1805388 and XRCC4 rs1805377 polymorphisms and tobacco smoking with respect to the risk of gliomas." (PMID 23663450, 2013). "The genetic polymorphism of XRCC4 has been frequently reported in liver cancer and glioma." (PMID 32915819, 2020). "Interestingly, we detected a significant additive and multiplicative interaction effect between the LIG4 rs1805388 and XRCC4 rs1805377 polymorphisms with an increasing risk of gliomas." (PMID 23663450, 2013). "Similarly, compared with the common homozygous genotype, carriers with XRCC4 rs1805377 homozygous variant genotype showed a significantly increased risk of gliomas (adjusted OR, 1.77; 95% CI, 1.12-2.80 for GG)." (PMID 23663450, 2013). "Furthermore, significant more-than-multiplicative (0.005) and more-than additive (0.009) gene-gene interactions of these two loci (LIG4 rs1805388 CT+TT and XRCC4 rs1805377 AG+GG) were found in relation to the risk of gliomas." (PMID 23663450, 2013). "Thus, we estimated the combined effect of LIG4 and XRCC4 genes on glioma risk." (PMID 23663450, 2013). "XRCC4 promotes DNA double-strand break repair and thus enhances cell survival and inhibits apoptosis in glioma cells in response to TMZ treatment." (PMID 36819921, 2023). "Mechanically, X-ray cross-complementing gene 4 (XRCC4) was directly targeted by miR-151a, and the repression of miR-151a elevated XRCC4 levels, activating DNA repair and increasing the resistance of glioma to TMZ." (PMID 35095909, 2021). "The expression of the XRCC4 gene is considerably down-regulated in many glioma cells, confirming the critical role of XRCC4 in brain tumors." (PMID 32746854, 2020). "We also found that the homozygous variant genotype (GG) of XRCC4 rs1805377 (IVS7-1A>G, splice-site) was associated with a significantly increased risk of gliomas (OR, 1.77; 95% CI, 1.12-2.80)." (PMID 23663450, 2013). "In addition, transcription factor zinc finger E-box binding homeobox 1 (ZEB1) upregulates the level of X-ray repair cross complementing 4 (XRCC4) expression via the SBF2-AS1/miR-151-3p axis to enhance resistance to temozolomide in glioma cell lines." (PMID 34372871, 2021). "In conclusion, of the 10 potential functional polymorphisms investigated here, we provide the first evidence that the XRCC4 rs1805377 (IVS7-1A>G, splice-site) and LIG4 rs1805388 (Ex2 +54C>T, Thr9Ile) polymorphisms contribute to the risk of developing gliomas, alone or in combination." (PMID 23663450, 2013). "Previous researches on the function of the XRCC4 rs1805377 and LIG4 rs1805388 polymorphisms have been informative in understanding the potential roles of these two polymorphisms in the development of gliomas." (PMID 23663450, 2013). "In comparison with the reference combination of LIG4 rs1805388 CC and XRCC4 rs1805377 AA, the combination of the LIG4 rs1805388 CT+TT genotype together with XRCC4 rs1805377 AG+GG genotype was found to be significantly associated with glioma (adjusted OR, 2.22; 95% CI, 1.49-3.30)." (PMID 23663450, 2013). "XRCC4 rs1805377 and LIG4 rs1805388 polymorphisms may be useful susceptibility biomarkers for gliomas and aid in the development of diagnostic strategy to reduce the burden of gliomas." (PMID 23663450, 2013). "Here we investigate the role of 10 potential SNPs in XRCC3, BRCA2, RAG1, XRCC5, LIG4, XRCC4 and ATM in the development of gliomas, and further evaluate their gene-gene and gene-environment interactions in the development of glioma." (PMID 23663450, 2013). "Furthermore, it has been shown that SBF2-AS1 depletion reduces the level of XRCC4, delays the repair of TMZ-induced DNA damage, and increases glioma cell sensitivity to TMZ." (PMID 36819921, 2023).
glioma (continued). "Two recent genome-wide association studies (GWAS) of risk of glioma in European populations did not identify an association between the XRCC4 rs1805377 and LIG4 rs1805388 polymorphisms and glioma risk." (PMID 23663450, 2013). "First, we were not able to explore the exact biological mechanism of how XRCC4 rs1805377 and LIG4 rs1805388 polymorphisms affect the development of gliomas." (PMID 23663450, 2013). "We genotyped 10 potentially functional single nucleotide polymorphisms (SNPs) in 7 DNA double-strand break repair pathway genes (XRCC3, BRCA2, RAG1, XRCC5, LIG4, XRCC4 and ATM) in a case–control study including 384 glioma patients and 384 cancer-free controls in a Chinese Han population." (PMID 23663450, 2013).
microcephaly (10 papers, 2013 to 2025). A congenital or acquired developmental disorder in which the circumference of the head is smaller than normal for the person's age and sex. "Noteworthy, XRCC4 mutations have been identified in individuals displaying global growth failure and microcephaly, apart from other variable clinical symptoms." (PMID 39035020, 2024). "In general, patients harboring XRCC4 mutations mainly show microcephaly, short stature, mental disabilities and facial dysmorphism." (PMID 37881689, 2023). "We generated XRCC4 mutants mimicking six of the mutations found in patients with microcephaly and growth defect." (PMID 33842963, 2021). "Several human patients with mutations in XRCC4 were reported to exhibit microcephaly and growth defects, but unexpectedly showed normal immune function." (PMID 33842963, 2021). "In the nervous system mutation or deletion of the NHEJ core components Lig4 or XRCC4 causes microcephaly, neuronal death during development, and promotes medulloblastomas with recurrent chromosome alterations." (PMID 23861962, 2013). "Homozygous missense mutations in XRCC4 can induce severe microcephaly." (PMID 37881689, 2023). "Phenotypically, mutations in XRCC4 can induce microcephaly and growth delay." (PMID 37881689, 2023). "Pathogenic variants in DCLRE1C (Artemis) and XRCC4/Ligase IV that may also include microcephaly and developmental delay where described in association with leukemia and lymphoma." (PMID 35967585, 2022). "In cones, several genes associated with cell migration (LARGE1), mechanistic target of rapamycin (mTOR) signaling (RICTOR), microcephaly (XRCC4), and intellectual developmental disorder (FMN2) were strongly dysregulated." (PMID 40706588, 2025). "On the other hand, growth defect and microcephaly, which are manifested in patients with XRCC4 mutation, are not observed in AOA1/EAOH." (PMID 36940705, 2023). "Similarly, microcephaly also results from mutation in genes associated with S phase progression (ATR, ATRIP, CtIP—Seckel syndrome; DNA ligase IV—lig4 syndrome; XRCC4—microcephalic primordial dwarfism)." (PMID 34035299, 2021). "In accordance, a recent study of a knock in Xrcc4M61R mouse model avoiding Lig4 disruption showed rescued embryonic lethality and only a modest increase in apoptotic cells in the intermediate zone, indicating that microcephaly in XRCC4 syndrome may arise due to LIG4 destabilization." (PMID 37881689, 2023).
bladder cancer (7 papers, 2007 to 2024). "Previous studies have reported that XRCC4 polymorphisms were related to the risk of prostate cancer, lung cancer and bladder cancer." (PMID 36765282, 2023). "Longer survival among patients with non-invasive tumors associated with XRCC4 polymorphism (SNP rs2662238) was found in patients with bladder cancer." (PMID 28684677, 2017). "To date, more than forty genetic polymorphisms based on mutations have been found in XRCC4, some of which are related to malignant tumors such as hepatocellular carcinoma, gastric cancer, oral cancer, bladder cancer, and esophageal cancer." (PMID 24378850, 2013). "In fact, overexpression of DNA-PKcs, LIG4 and XRCC4 is correlated with poor prognosis in several cancer types, such as esophageal cancer, colorectal cancer, bladder cancer, ovarian cancer, and hepatocellular cancer." (PMID 38380364, 2024). "XRCC4 was well studied in diverse human tumors such as lung carcinoma 22 and bladder carcinoma 23, which was reported as a poor productive factor in these cancers." (PMID 34539898, 2021). "The XRCC4 polymorphism (SNP rs1805377) (splice site 1) is associated with genetic susceptibility to RCC, glioma, NSCLC, and bladder cancer, and patients with this SNP had significant genomic instability and poor prognosis." (PMID 28684677, 2017).
B-cell lymphomas (6 papers, 2015 to 2022).
colorectal cancer (6 papers, 2010 to 2024). A primary or metastatic malignant neoplasm that affects the colon or rectum. "To examine the genetic association between colorectal cancer and schizophrenia, we analyzed five SNPs (rs6452526, rs2662238, rs963248, rs35268, rs2386275) covering ~205.7 kb in the region of XRCC4." (PMID 20920336, 2010). "Similarly, XRCC4 c.1394G>T G/T genotype has been associated with breast, gastric, and prostate cancers among Taiwanese and colorectal cancer among Iranians." (PMID 31030479, 2019). "In a genetic study of schizophrenic Chinese Han patients, XRCC4 gene polymorphisms may be protective against colorectal cancer risk." (PMID 29254248, 2017). "XRCC4 is one of the potential candidate genes associated with schizophrenia which might induce colorectal cancer resistance." (PMID 20920336, 2010). "We therefore concluded that variants within the XRCC4 gene might confer genetically reduced susceptibility to colorectal cancer among patients with schizophrenia." (PMID 20920336, 2010). "Our data firstly indicate that XRCC4 may be a potential protective gene towards schizophrenia, conferring reduced susceptibility to colorectal cancer in the Han Chinese population." (PMID 20920336, 2010). "In summary, our results provide a first indication that XRCC4 might be a potential protective gene with respect to schizophrenia, conferring decreased susceptibility to colorectal cancer in the Han Chinese population." (PMID 20920336, 2010). "Functional studies in colorectal cancer cells revealed that LTR10 elements regulate tumor-specific expression of multiple genes associated with tumorigenesis, such as ATG12 and XRCC4." (PMID 39018396, 2024). "The X-ray repair complementing defective repair in Chinese hamster cells 4 (XRCC4) gene is located on chromosome 5q14.2, which showed loss of heterozygosity (LOH) in sporadic colorectal cancer (Ratio 37.7%), and high ratio LOH indicates the presence of tumor suppressor locus." (PMID 20920336, 2010).
hepatocellular carcinoma (6 papers, 2013 to 2024). A malignant tumor that arises from hepatocytes. "Large studies on the role of XRCC4 single-nucleotide polymorphisms (SNPs) in cancer susceptibility have been performed in hepatocellular carcinoma, lung cancer, multiple myeloma, and oral cancer." (PMID 25360583, 2014). "Our previous investigations have shown that the variants of X-ray repair complementing 4 (XRCC4) may be involved in hepatocellular carcinoma (hepatocarcinoma) tumorigenesis." (PMID 29152133, 2017). "Consistent with the findings of the present study, previous researches have confirmed that XRCC4 overexpression in uterine cervical cancer, esophageal cancer and hepatocellular carcinoma." (PMID 36765282, 2023). "In hepatocellular carcinoma (HCC), the novel lncRNA NIHCOLE acts as a scaffold and facilitates the formation of multimeric complexes involving Ku70/80, APLF, XRCC4, and DNA ligase IV to promoting the ligation efficiency of DNA DSBs." (PMID 38012734, 2023).
lymphoma (6 papers, 2010 to 2025). A malignant (clonal) proliferation of B- lymphocytes or T- lymphocytes which involves the lymph nodes, bone marrow and/or extranodal sites. "DSBs caused by etoposide (VP16), a topoisomerase II inhibitor, are primarily repaired by NHEJ, manifested by the strong sensitivity in XRCC4-depleted DT40 cells (chicken lymphoma cells)." (PMID 41359381, 2025). "Since Xrcc4 was deleted in the GC B cells, these lymphoma cells harbored normal D-J or V-D-J recombination junctions at the Igh locus (junction 1 and 2, respectively)." (PMID 26740101, 2016). "However, lymphomas with chromosome translocations are observed in classical NHEJ-defective, ligase IV/XRCC4 deficient, mice." (PMID 21048951, 2010).